TRBV24-1 (T cell receptor beta variable 24-1)
Description:
V region of the variable domain of T cell receptor (TR) beta chain that participates in the antigen recognition. Alpha-beta T cell receptors are antigen specific receptors which are essential to the immune response and are present on the cell surface of T lymphocytes. Recognize peptide-major histocompatibility (MH) (pMH) complexes that are displayed by antigen presenting cells (APC), a prerequisite for efficient T cell adaptive immunity against pathogens. Binding of alpha-beta TR to pMH complex initiates TR-CD3 clustering on the cell surface and intracellular activation of LCK that phosphorylates the ITAM motifs of CD3G, CD3D, CD3E and CD247 enabling the recruitment of ZAP70. In turn ZAP70 phosphorylates LAT, which recruits numerous signaling molecules to form the LAT signalosome. The LAT signalosome propagates signal branching to three major signaling pathways, the calcium, the mitogen-activated protein kinase (MAPK) kinase and the nuclear factor NF-kappa-B (NF-kB) pathways, leading to the mobilization of transcription factors that are critical for gene expression and essential for T cell growth and differentiation. The T cell repertoire is generated in the thymus, by V-(D)-J rearrangement. This repertoire is then shaped by intrathymic selection events to generate a peripheral T cell pool of self-MH restricted, non-autoaggressive T cells. Post-thymic interaction of alpha-beta TR with the pMH complexes shapes TR structural and functional avidity.
Synonyms: TRBV241; TCRBV15S1; TCRBV24S1
Gene: T-cell receptor variable (V) gene on chromosome 7 (142,656,701 to 142,657,213, forward strand). Ensembl gene ENSG00000211750.
Subcellular location: Cell membrane
Gene Ontology:
Biological process: cell surface receptor signaling pathway
Cellular component: plasma membrane
Homologues: Orthologues: chimpanzee TRBV24-1 (83% identical), macaque TRBV24-1 (77% identical), dog TRBV24-1 (69% identical), guinea pig TRBV24-1 (63% identical). Paralogues in human: TRBV10-3 (57% identical), TRBV10-1 (54% identical), TRBV6-2 (53% identical), TRBV10-2 (51% identical), TRBV25-1 (51% identical), TRBV27 (51% identical), TRBV28 (51% identical), TRBV6-1 (51% identical), TRBV6-6 (51% identical), TRBV6-7 (51% identical), TRBV6-4 (50% identical), TRBV6-8 (49% identical), and 39 more.